E2F1 (E2F transcription factor 1)
Diseases named in the same sentence as E2F1 in open-access papers (continued):
Sharing a sentence is not in itself a finding about the gene and the disease.
melanoma (continued). "E2F1 levels were not altered by MYC-depletion in melanoma cells indicating that under-expression of TS and RR and depletion of dNTP pools in senescent melanoma cells is likely to be a direct consequence of C-MYC suppression." (PMID 23249808, 2012). "To assess the status of E2F-1 during melanoma progression, we performed Western Blot analysis in non-metastatic and metastatic melanoma cell lines." (PMID 20805990, 2010). "Importantly, disruption of this complex, without altering the levels of SLNCR1 or E2F1, significantly reduces the invasive capacity of melanoma cells." (PMID 41463281, 2025). "Its pro cancer mechanism mainly includes two aspects: on the one hand, DTL promotes the malignant progression of melanoma by reshaping the glucose metabolism process of tumor cells; On the other hand, it drives the proliferation and migration of melanoma cells via the ERK/E2F1/BUB1 signaling axis." (PMID 41409301, 2025). "As a first step in order to understand if the selected E2F target genes could function as predictor markers of CDK4/6 inhibition resistance, we compared the expression profiles of E2F1, CDC6, DHFR, H2AFZ, MCM2, and ATAD2 among the four canine melanoma cell lines." (PMID 34485433, 2021). "Whilst it has been established the somatic amplification of E2F1 in melanoma, germline E2F1 copy number in melanoma patients has never been determined, in this study, we wanted to verify whether pre-existing CNVs of this gene might also predispose to melanoma." (PMID 31142321, 2019). "Interestingly, cooperative repression by E2F1 and CREB has been recently demonstrated in the transcriptional regulation of AP-2a, a tumor suppressor gene involved in the malignant phenotype of melanoma, whose promoter harbors three CRE-like sites and one E2F site necessary for its regulation." (PMID 24038359, 2013). "In contrast, E2F-1 promoter induction by HAdV-5 infection was minimal or lacking in melanoma cells." (PMID 22140489, 2011). "Moreover, miR-221 targets are the E2F transcription factor 1 (E2F1), the phosphatase and tensin homolog (PTEN) and the cyclin-dependent kinase inhibitor 1 (CDKN1A), all belonging to critical cancer related pathways in HCC as well as other types of cancer including melanoma." (PMID 31906510, 2020). "However, it had not been described whether CREB regulates E2F-1 expression at the transcriptional level during melanoma progression." (PMID 20805990, 2010). "Molecular studies of melanoma cells with absent SOX10 showed reduced expression of MITF, elevated expression of p21/WAF1 and p27KIP2, hypophosphorylated RB, and reduced levels of E2F1." (PMID 38132479, 2023).
glioma (95 papers, 2010 to 2026). A benign or malignant brain and spinal cord tumor that arises from glial cells (astrocytes, oligodendrocytes, ependymal cells). "On the other hand, one of the first studies reporting the tumor-suppressive effect of miR-106a in GBM demonstrated that the low expression of miR-106a in human glioma specimens is associated with the accumulation of E2F1 protein and high-grade glioma." (PMID 37627777, 2023). "Lastly, we proved that SMC4, which has the highest positive regression coefficient in our risk model, is strongly linked with malignant progression and TMZ resistance of gliomas in a E2F1‐dependent manner." (PMID 35615996, 2022). "Downregulation of E2F1 by miRNAs has been observed to be associated with reduced proliferation of glioma cells." (PMID 34758200, 2021). "Overexpression of E2F1 blocked the proliferation repression caused by miR-342-3p or miR-377 in glioma cells, and E2F1 overexpression conferred resistance to cisplatin in glioma cells." (PMID 33381564, 2020). "The network topology analysis performed in this study revealed a set of central nodes associated to glioma malignancy, such as Map3k14, Mapk1, Actn4, Hspa5, Atf2, Rac1,E2f1, Shc1, Pik3ca, Akt1, Vim and Egr1." (PMID 26582089, 2015). "E2F1 overexpression in glioma cells can cause the phosphorylated level of Akt increase, interfering with the expression of E2F1 can decrease the phosphorylated level of Akt." (PMID 23866847, 2013). "At present, only few oncogene addictions have been identified in gliomas except for E2F1 addiction, and some classical glioma-associated genes may be potential oncogene addictions." (PMID 21575270, 2011). "A distinct glioma stem cell population was identified, characterized by high proliferative potential and an enrichment of E2F1, E2F2, E2F7, and BRCA1 regulons, with implications for tumor growth and patient outcomes." (PMID 39981232, 2025). "Several genes included in our signature, notably NOTCH1, NES, E2F1 and EGFR, have been implicated in glioma adaptation to temozolomide (TMZ) therapy, where changes in their expression or activity influence stemness, invasion and drug resistance." (PMID 41375052, 2025). "ECT2 promoted glioma cell proliferation by regulating the expression of the deubiquitinating enzyme PSMD14 to affect the degradation of the TF E2F1." (PMID 38467631, 2024). "Our results suggest that E2F1 is a key transcription factor in EGFRvIII-positive glioma cells and quickly responds to TMZ treatment." (PMID 37283490, 2023). "We analyzed E2F1 expression in an intracranial glioma model by IHC staining and showed that TMZ significantly increased E2F1 protein levels in vivo." (PMID 37283490, 2023). "We demonstrated that E2F1 is a key transcription factor in EGFRvIII-positive glioma cells and profiled the functions of E2F1 in TMZ resistance." (PMID 37283490, 2023). "As a well-known oncogenic transcription factor, E2F-1 is upregulated in various tumors, including glioma, and promotes tumor progression." (PMID 38017538, 2023). "E2F1 has been reported to be upregulated by PDGF in gliomas and supports pro-neural glioma progression by enhancing USP1 expression." (PMID 37283490, 2023). "We analyzed the expression of E2F1 mRNA in glioma cells To study the regulation of EGFRvIII and TMZ on E2F1 to study EGFRvIII and TMZ regulation of E2F1." (PMID 37283490, 2023). "In both TCGA and Gravendeel cohorts, gliomas with a STAT3high gene signature (associated with inferior glioma patient survival and GBM) significantly expressed higher E2F1 and H2AZ2 levels than tumors with a STAT3low gene signature." (PMID 35058574, 2022). "To confirm the regulation role of E2F1 for SMC4, we performed E2F1 silencing in glioma tumour cells." (PMID 35615996, 2022). "The results showed E2F1 expressed highest in both glioma tissues and GSCs than NBT and NHA resprespectively (Sup." (PMID 35371308, 2022).
glioma (continued). "Mechanistically, studies have revealed that the JNK pathway, NOTCH pathway, RAS/MYC axis and Rb/E2F1 pathway participate in the development of H3.3K27M-positive gliomas." (PMID 36230759, 2022). "These associations were validated for each of these transcription factors, excluding E2F1, in at least three additional glioma cohorts, including the SUN, KAWAGUCHI, FRENCH, or FREIJE datasets." (PMID 35228525, 2022). "Mechanistically, it is revealed that E2F1 is a regulator for SNHG18/miR-338-5p/FOXD1 axis in glioma." (PMID 34937497, 2022). "Our data suggest that SNHG18/miR-338-5p/FOXD1 axis is a vital downstream mechanism by which E2F1 participates in regulating glioma progression." (PMID 34937497, 2022). "E2F1 is significantly up-regulated in glioma tissues, and it is a crucial transcription factor involved in maintaining the malignancy of glioma cells, and it is considered as a promising therapy target." (PMID 34937497, 2022). "The TCGA microarray databases illustrated that the expression levels of E2F1 increased with ascending pathological grade of glioma (p < 0.001)." (PMID 34079762, 2021). "One study revealed that miR-136 remarkably repressed E2F1 expression to promote CDDP chemosensitivity in glioma cells." (PMID 34726120, 2021). "To investigate the role of CDDP, miR-485-5p, or E2F1 in glioma cells, we evaluated the effects of CDDP combined with miR-485-5p or E2F1 expression on the viability, proliferation, apoptosis, and invasion of glioma cells." (PMID 34726120, 2021). "As expected, high expression of E2F1 was confirmed in the glioma tissues and cells, which showed an inverse trend with miR‐107." (PMID 34758200, 2021). "This study provides a novel mechanistic basis and strategy for clinical application of CDCA8/E2F1 in glioma in the future." (PMID 33542211, 2021). "Here, we found CCND1 was highly expressed in glioma tissues and cells, and its expression was reduced by miR‐107, but reduced by E2F1." (PMID 34758200, 2021). "Another study showed that adenovirus-mediated transfer of E2F-1 potentiated the chemosensitivity of human glioma cells to TMZ and BCNU." (PMID 34726120, 2021). "During this study, we identified that Pontin was overexpressed in gliomas and possessed tumor-promoting capacities as a transcription co-activator of E2F1, thereby controlling cell cycle progression and cell growth." (PMID 33542204, 2021). "This is also true for glioma, because upregulation of E2F1 has been correlated with proliferation, cell cycle progression, and carcinogenesis of glioma." (PMID 34758200, 2021). "In this study, we revealed that CDCA8 synergized with E2F1 facilitated the proliferation and migration of glioma." (PMID 33542211, 2021). "Taken together, these results demonstrated that FGF14-AS2 promotes the proliferation, migration and invasion of glioma cells via the miR-320a/E2F1 axis." (PMID 34659533, 2021). "In conclusion, despite the limited numbers of clinical specimens and relatively preliminary mechanism research, we defined CDCA8 as a novel tumor promotor in the development of glioma probably through regulating E2F1." (PMID 33542211, 2021). "First, we identified the key miRNA (miR-485-5p) and target gene (E2F1) through bioinformatics analysis and found that CDDP treatment upregulated miR-485-5p levels in glioma cells and downregulated E2F1 levels." (PMID 34726120, 2021). "Nevertheless, our findings demonstrate that Pontin is a vital cell cycle regulator at least by amplifying E2F1 transcription response in glioma, shedding light on the possibility of targeting Pontin for anti-glioma therapy." (PMID 33542204, 2021). "In glioma, miR-197-5p interacted with lncRNA DLX6-AS1 and suppressed transcription factor E2F1 expression, thus dampened glioma development and progression." (PMID 33442405, 2021).
glioma (continued). "Existing studies have shown that E2F1 is dysregulated in various types of human cancers including glioma." (PMID 33542211, 2021). "The binding of transcription factors at the SMC4 promoter region is predicted and MYB and E2F1 are identified as potential transcription factors for SMC4 in glioma patients." (PMID 34868977, 2021). "Deregulation of E2F transcription factor, specifically E2F-1 is a critical target of any alteration of the p16/Rb/E2F pathway in glioma." (PMID 33790740, 2021). "Taken together, these results suggested that FGF14-AS2 acts as a ceRNA to regulate the miR-320a/E2F1 axis and is thus involved in the malignant progression of glioma." (PMID 34659533, 2021). "LncRNA DLX6-AS1 upregulation enhances proliferation and invasion of glioma cells through sponging miR-197-5p to upregulate E2F1 expression." (PMID 33589577, 2021). "E2F5, E2F7, and E2F8 were significantly upregulated in brain and CNS cancers relative to normal brain samples, while E2F1 and E2F3 were more highly expressed in normal brain samples in the ONCOMINE dataset." (PMID 34617871, 2021). "E2F1 promotes cell cycle progression from G1 to S phase, and the stability of cell cycle activator E2F1 affects the glioma cell proliferation." (PMID 32764572, 2020). "In glioma carcinogenesis, DLX6-AS1 can endogenously sponge miR-197-5p to alleviate E2F1 and thus promote glioma development." (PMID 33216728, 2020). "Luciferase reporter assays also showed that the E2F1 transcriptional activity on these genes was suppressed in TMZ-resistant glioma cells treated with BIP-MPC-NP." (PMID 32001707, 2020). "In the presence of BIP-MPC-NP, DNA damage repair is attenuated and TMZ sensitivity is enhanced via the down-regulation of E2F1 mediated by TTP in TMZ resistant glioma." (PMID 32001707, 2020). "In glioma cells, the regulation of miR-372 and E2F1 appeared to be one molecular mechanism of the oncogenic effect." (PMID 31965534, 2020). "DLX6‐AS1 attenuates the inhibition of E2F1 through competitive binding to miR‐197‐5p, thereby accelerating the development of glioma." (PMID 32892482, 2020). "Subsequently, by down‐regulating FER1L4, we confirmed that E2F1 expression was also down‐regulated and that FER1L4 and E2F1 were involved in the cell cycle of gliomas (FER1L4 regulates the cell progression in G2‐M by regulating E2F1)." (PMID 30887657, 2019). "Further over‐expression of miR‐372 showed that the expression of FER1L4 and E2F1 was down‐regulated and the results further confirmed that as a ceRNA, FER1L4/miR‐372/E2F1 regulates the molecular mechanism of glioma cell proliferation." (PMID 30887657, 2019). "The study above showed that the expression of FER1L4 and E2F1 in different grades of glioma tissues showed a significant positive correlation." (PMID 30887657, 2019). "The results suggested a significant correlation between the expression of FER1L4 and E2F1 and the prognosis of glioma patients and the high expression of FER1L4 (P < 0.05) or E2F1 (P < 0.01) predicts a worse prognosis of gliomas." (PMID 30887657, 2019). "The results further proved that as a ceRNA, FER1L4/hsa‐miR‐372/E2F1 regulates the molecular mechanism of glioma cell proliferation." (PMID 30887657, 2019). "There was a significant positive correlation between its expression in gliomas and FER1L4 expression suggesting a synergistic effect between FER1L4 and E2F1, which participate in the malignant biological process of glioma." (PMID 30887657, 2019).
glioma (continued). "Taken together, a mechanistic link between LSH expression and activation of the LPR6/GSK3β/E2F1 axis in glioma illustrates a novel role of LSH in malignant astrocytomas and GBM." (PMID 30498431, 2018). "Research indicates that the up-regulated transcription factor E2F1 and glycogen synthase kinase-3β (GSK-3β, an intact complex of E2F1) in astrocytomas and GBM were associated with the progression of glioma and correlated with LSH expression." (PMID 30498431, 2018). "In view of this, we focused our attention on investigating the interactions between KPNA2, c-myc and E2F1 in the glycolytic transformation of gliomas." (PMID 30115078, 2018). "While the position of E2F1 as a prognosis marker of glioma is debated, abnormalities of the p16/pRb/E2F pathway with over-expression of E2F are present in most of gliomas and suggest E2F1 as a potential therapeutic target." (PMID 28467792, 2017). "It has been previously shown that overexpression of E2F1 in glioma cell lines induced apoptosis through the activation of caspases in these cell lines." (PMID 28081256, 2017). "E2F1, involved in glioma pathways, was strongly down-regulated in B104 cells; its modulation was not explored in human cell lines." (PMID 28467792, 2017). "To our knowledge, we are the first to propose that the E2F1/miR-19a/PPARα feedback loop is a key regulatory element in glioma." (PMID 27835866, 2016). "PPARα inhibits glioma cell proliferation, invasion, and aerobic glycolysis, and suppresses glioma growth in an orthotopic model via a positive feedback loop with E2F1 and miRNA-19a." (PMID 27835866, 2016). "In human glioma samples, Pearson's correlations showed a significantly positive correlation between between E2F1 and miR-19a." (PMID 27835866, 2016). "E2F1 and miR-19a expression were markedly decreased following up-regulation of PPARα in a nude mouse glioma xenograft model." (PMID 27835866, 2016). "In glioma tissues, pearson correlation showed a significant positive correlation between E2F1 and miR-19a levels (R = 0.66, P < 0.01)." (PMID 27835866, 2016). "The depletion of E2F1/miR-19a signaling inhibited glioma cell proliferation, invasion and aerobic glycolysis accompanying the downregulation of PPARα." (PMID 27835866, 2016). "Overexpression of E2F1 protein and the activation of E2F-responsive promoters have been reported, by our group and others, to occur in gliomas and consequently, VCN-01 replication is expected to proceed in glioma cells." (PMID 26808201, 2016). "This miRNA family is one of the most abundant in gliomas, and a validated transcriptional target of E2F1." (PMID 25738367, 2015). "The coordinated regulation of numerous E2F1 transcription targets, both mRNAs and miRNAs, by miR-10b in glioma, suggests this miRNA as a powerful regulator of glioma growth and, particularly, E2F1–driven oncogenesis." (PMID 25738367, 2015). "Qur analysis revealed that restoring miR-329 expression attenuated protein level of E2F1 by posttranscription regulation, and inhibited cell cycle progression in glioma." (PMID 23866847, 2013). "We constructed cell models of over-expressing miR-329 and down-expressing miR-329 in glioma cells and screened expressing levels of miR-329 and E2F1 in a group of glioma cells." (PMID 23866847, 2013). "MiR-106a suppressed cell proliferation and induced cell apoptosis in glioma cells by targeting E2F1." (PMID 24124917, 2013). "MiR-34a, the expression of which is diminished in glioma cells, targets the mRNAs of multiple growth-promoting genes, including E2F transcription factor 1 (E2F1), hepatocyte growth factor receptor (c-met), and CCND1." (PMID 24202447, 2013).